ALK (ALK receptor tyrosine kinase)
Diseases named in the same sentence as ALK in open-access papers (continued):
Sharing a sentence is not in itself a finding about the gene and the disease.
tumor (continued). "Decreased autophagic flux in ALK+ ALCL plays a role in drug resistance, and tumor cells are regulated in various ways that lead to inhibition of autophagy and crizotinib resistance including regulation of miRNAs and Bcl-2 expression." (PMID 35211406, 2022). "Research on tumor vaccines and chimeric antigen receptor T-Cell (CAR-T cell) therapy targeting ALK are also underway." (PMID 35958559, 2022). "They described the case report of an ALK-RCC patient who relapsed after complete resection of the tumor and, therefore, received first-line treatment with entrectinib, a selective TKI towards neurotrophic tyrosine receptor kinase (NTRK), ROS1, and ALK fusion." (PMID 35409355, 2022). "Sanger sequencing of ALK and PHOX2B, SNP microarray of three tumor samples and whole genome sequencing of tumor and blood were performed." (PMID 36140661, 2022). "In xenograft models of ALK-positive NSCLC, conteltinib showed marked anti-tumor activity both in crizotinib-sensitive and crizotinib-resistant tumors." (PMID 36424628, 2022). "Indeed, analyses of circulating tumor cells revealed high levels of chromosomal instability in ALK-positive NSCLC patients that were resistant to ALK inhibitor treatment, and it will be interesting to determine whether this correlates with the EML4-ALK variant expressed." (PMID 35656694, 2022). "Next, we evaluated the clinical relevance of our findings by analysis of p-ALK- and p-Tyr19-CDK9 in tumor tissue from cancer patients." (PMID 36253486, 2022). "Similar to this, in an ALK-resistant ALK+ ALCL patient whose tumor tissue highly expresses PD-L1, the tumor tissue completely disappeared after 5 months of Navumab treatment and the complete remission was maintained for up to 18 months." (PMID 35211406, 2022). "In ALK rearranged NSCLC, the aim of ALK directed vaccines is to convert the immunosuppressive TME into an immunoreactive TME, thereby stimulating the migration of TILs to the tumour microenvironment to kill tumour cells." (PMID 36591504, 2022). "Ceritinib inhibits not only ALK but also secondary mutations of ALK, including L1196M, G1269A, S1206Y, and I1171T EML4-ALK mutants, and IGF1R, which plays a significant role in tumor growth and is overexpressed in several CNS metastases." (PMID 36508072, 2022). "Conteltinib has effective anti-tumor activity not only in ALK TKI-naïve, advanced ALK-positive NSCLC patients (ORR=64.1%), but also in patients who received crizotinib previously (ORR=33.3%)." (PMID 36424628, 2022). "Longitudinal plasma samples (n = 79) of 21 ALK-positive NSCLC patients and 13 healthy donors were collected alongside 15 ALK-positive tumor tissue and 10 healthy lung tissue specimens." (PMID 36461127, 2022). "Tumor driver genes in NSCLC patients have been uncovered one by one, including epidermal growth factor receptor (EGFR), mesenchymal lymphoma kinase (ALK), and receptor tyrosine kinase ROS proto-oncogene 1 (ROS1) mutants." (PMID 36499382, 2022). "Following their comments, we performed an additional immunohistochemistry (IHC) analysis of the tumor by using ALK (D5F3) (clone D5F3, ready to use; Roche), and the tumor showed diffuse cytoplasmic and diffuse strong membranous positivity." (PMID 35718773, 2022). "A majority of ALK-positive NSCLCs lack concurrent PD-L1 expression and high levels of CD8+ tumor infiltrating lymphocytes (TILs)." (PMID 35958559, 2022). "Similarly, tumor-specific ALK fusions or mutants may also be recognized as neoantigens in the body." (PMID 35958559, 2022). "One of the compounds, PROTAC 38, effectively induced ALK degradation and inhibited the growth of the ALK fusion-positive cell line SU-DHL-1 and the human NSCLC cell line H3122, and also inhibited tumor growth in the H3122 xenograft model." (PMID 36142231, 2022).
tumor (continued). "The combination of an ALK TKI with HSP90 inhibition not only yielded synergism in Ba/F3 cells expressing EML4-ALK V1, but also induced apoptosis in vitro and tumour regression in vivo of patient-derived cells expressing V1." (PMID 35884511, 2022). "The current mandatory biomarkers to look for in late-stage NS-NSCLC include different genomic alterations present on EGFR, ALK, ROS1, NTRK, BRAF, MET, and RET, as well as the PD-L1 expression of tumor cells." (PMID 35565387, 2022). "The mechanism of action is represented by the inhibition of the autophosphorylation of ALK gene and the molecular targets include IGF-1 R, InsR, and ROS1 and have an activity of 20 times higher against crizotinib–resistant tumor cell lines." (PMID 34082691, 2022). "ALK TKIs (alectinib, brigatinib, ceritinib, etc.)are often used as PROTAC ligands to promote the degradation of ALK protein and thereby inhibit tumor growth driven by ALK." (PMID 35211406, 2022). "The combination of this vaccine and ALK TKI is also effective and significantly delayed tumor relapse after TKI treatment." (PMID 35958559, 2022). "Among ALK-rear-racking NSCLC combined LM patients, CSF liquid biopsy can be more sensitive to targeted changes and monitor tumor reactions." (PMID 36601482, 2022). "In conclusion, our findings indicate that CD147 is of vital importance for ALK+ ALCL to maintain the high energy demand of rapid cell proliferation, promoting lactate export, and tumor growth." (PMID 35676454, 2022). "Although ALK fusion is a clinically proven tumor therapeutic target, compared with other carcinogenic drivers, such as epidermal factor growth receptor (EGFR), how to better target ALK fusion lacks accuracy." (PMID 36290895, 2022). "Different in vitro studies have demonstrated a concentration-dependent inhibition by crizotinib of tyrosine phosphorylation mediated by ALK, ROS1, and MET in different tumor cell line-based assays." (PMID 35565287, 2022). "Compared to ALK− LUAD, ALK+ LUAD possesses a relative “cold” TIME, with less TLS formation and TLS-ICs, which was closely correlated with tumor progression." (PMID 36233802, 2022). "Compared to ALK− tumors, ALK+ tumors showed significantly weaker TLS formation, reflected by the lower TLS density, lower TLS/tumor, and lower densities of all main TLS-ICs, including tB cells, tTh cells, and tCTL." (PMID 36233802, 2022). "To evaluate the diagnostic performance of cfDNA‐NGS, we analyzed the detection rate of ALK alterations by cfDNA‐NGS in the ALK rearranged NSCLC patients who had been diagnosed by ALK IHC, FISH, or targeted NGS from tumor tissue." (PMID 35437925, 2022). "Comparable to primary tumor cell lines, CRISPR/Cas9 knock-out of PDGFRβ in ALK+ cells also led to a decrease in proliferation when seeded at a low cell density." (PMID 36045346, 2022). "We focused on CD147, because we recently reported that this protein is induced by C/EBPβ and it is differentially expressed in ALK+ versus ALK− ALCL cases, indicating a specific role of CD147 in ALK+ ALCL tumor development." (PMID 35676454, 2022). "Two out of three patients with metastatic ALK-rearranged LCNEC received up-front treatment with the ALK TKI alectinib and showed rapid tumor response at all metastatic sites, including multiple brain metastases." (PMID 35756632, 2022). "NSCLC patients with recurrent metastatic disease are subsequently eligible for targeted systemic therapy if the tumor expresses clinically actionable genetic alterations such as EGFR, ALK, MET, RET, and ROS1." (PMID 35448189, 2022). "Although most ALK+ ALCLs show a monoclonal rearrangement of the TCR genes, the tumor cells often lack T-cell antigen expression." (PMID 36010351, 2022). "Some tumors had molecular aberrations in frequently altered genes in NSCLC such as ALK, EGFR, KRAS or ROS1, as determined with the TruSight Tumor 170 sequencing panel in-house." (PMID 35329826, 2022).
tumor (continued). "Another case identified an EML4::ALK rearrangement in LCNEC with crizotinib resistance, suggesting that perhaps ALK-positive LCNEC is derived from ALK-positive ACA via tumor plasticity." (PMID 35200571, 2022). "Sufficient tumor material was available from fourteen patients treated with certolizumab (14/18; 78%) for EGFR, KRAS, BRAF, ERBB2, and ALK testing and from ten patients (10/18; 56%) for NGS." (PMID 36241629, 2022). "However, G1202R was shown to reduce the sensitivity of tumor cells to brigatinib and loratinib, and tumor cells harboring double mutations (D1203N+E1210K and F1174C+D1203N) had lower sensitivity to loratinib, whereas none of the second-generation ALK TKIs were effective." (PMID 35211406, 2022). "Druggable fusion events were identified in 7.1% (5/70) of tumor specimens: FGFR3-TACC3 (n = 2), NTRK2 fusions (n = 1), ALK (n = 1), and ROS1 (n = 1)." (PMID 34234122, 2021). "Tumor cells were positive for CD3 and granzyme B. CD30 was diffusely positive and ALK was also diffusely expressed in cytoplasm and nuclei." (PMID 34072328, 2021). "As several earlier series and preclinical studies have shown, ALK- and EGFR-driven tumors have an immunosuppressive tumor microenvironment with resistance to programmed cell death protein 1 (PD-1) and programmed cell death 1 ligand 1 (PD-L1) inhibitors." (PMID 33494549, 2021). "In order to validate the microarray data, TCLlnc1 expression was detected by qRT-PCR in tumor samples of 70 PTCL patients, including 9 cases of ALK+ALCL, 6 cases of ALK−ALCL, 23 cases of AITL, and 32 cases of PTCL-NOS, as well as 16 cases of RH." (PMID 33767152, 2021). "Of the 1117 patients included, 420 (38%) had KRAS mut tumours, 142 (13%) had EGFR mut tumours, 12 (1%) had ALK rearranged tumours, and 3 (0.3%) patients had ROS1 rearranged tumours." (PMID 34503114, 2021). "We utilized tissue microarrays constructed from 136 primary MCC tumor samples as well as nine previously established MCC cell lines to determine the presence of ALK and phosphorylated ALK (p-ALK) via immunohistochemistry." (PMID 34029351, 2021). "For example, in a mouse model of ALK+ ALCL where expression of NPM-ALK was driven in T cells by a CD4 promoter, tumour formation was only compromised when both c-Jun and JunB were knocked-out, and double knock-out cells exhibited impaired proliferation." (PMID 33413671, 2021). "More than 90 different ALK fusion partners have been discovered in NSCLC patients, and ALK tyrosine kinase inhibitors (TKIs) such as crizotinib and alectinib have achieved tumor responses in patients with advanced ALK-positive NSCLC." (PMID 34490099, 2021). "The current case series clarified the efficacy of ALK-TKIs, including alectinib, a second-generation ALK-TKI, across different tumor types and fusion partners in patients with advanced, ALK-rearranged, nonlung solid tumors." (PMID 34036223, 2021). "With the wide application of targeted drugs such as EGFR-TKIs and ALK-TKIs, NSCLC has become the most developed tumor type of precision medicine field." (PMID 34336662, 2021). "Eight cases were positive for ALK FISH (gene split, >20% tumor cells), and 14 cases were borderline-positive for ALK FISH (gene split, 15–20% tumor cells)." (PMID 34066104, 2021). "The F72 and F75 tumors shared genes mediating inflammation and angiogenesis, whereas ALK and ALPK2 kinases were specifically expressed in each tumor, respectively." (PMID 33853673, 2021). "The kinase inhibition leads to disruption of ALK- and ROS1-mediated signaling and eventually inhibits tumor cell growth in ALK- and ROS1-overexpressing tumor cells." (PMID 34443583, 2021). "Similar applies to patients with detection of multiple ALK resistance mutations: these might be originating from different tumor cell clones and do not necessarily correspond to compound ALK mutations, therefore they should not be used to exclude patients from a trial of lorlatinib." (PMID 33494549, 2021).
tumor (continued). "In these 76 patients, genomic profiling of 128 tumors by MSK-IMPACT yielded a median of 8 somatic alterations per tumor (range, 1–47), and a major oncogenic driver alteration (e.g., EGFR, KRAS, ALK, ROS1, or MET exon 14) was identified in 107 tumors (84%)." (PMID 34359558, 2021). "In summary, due to a large number of possible ALK TKI resistance mechanisms, it is essential that tumours are assessed at the time of resistance to identify the underlying cause, to inform on the next best therapeutic approach towards a cure." (PMID 34885113, 2021). "ALK break-apart FISH analysis showed that there was more aberrant chromosome 2 fragmented and scattered in tumor cells, probably because chromosome structure was damaged severely by chromothripsis." (PMID 34271921, 2021). "The tumor expression levels of receptor tyrosine kinase genes, including VEGFR-1, VEGFR-2, PDGFR-α, PDGFR-β, ALK, EGFR, ErbB2, and B-RAF, were analyzed." (PMID 33764261, 2021). "The clinical applications of this finding have been demonstrated in other tumor types such as NSCLC, where good concordance between ALK-rearranged CTCs and ALK-positive tumor biopsies has been demonstrated." (PMID 34280125, 2021). "ALK fusions binds to and activates PI3K through the regulatory p85 subunit of PI3K in tumor cells, leading to the phosphorylation of its downstream effectors AKT1 and AKT226." (PMID 34234236, 2021). "ALK activation occurs in all EIMS and 50% of IMTs, a finding which supports the neoplastic origin of the tumor, as ALK protein is known to have an oncogenic role in hematologic and solid tumors." (PMID 37206935, 2021). "Mesenchymal features are increasingly common in ALK-TKI-resistant tumor specimens, suggesting a role of EMT in resistance to ALK-TKIs as well." (PMID 33572278, 2021). "Most of these tumor-related alterations belong to the kinases from the closest animal counterpart RTKs, such as RON, FGFR1-4, IGF-1R, ALK, c-Ret, c-Met, and HER-2." (PMID 35095975, 2021). "This includes tumor gene sequencing as well as the use of specific targeted drugs for tumors with targetable alterations (e.g., EGFR, ALK, ROS1, NTRK, BRAF, or HER inhibitors)." (PMID 34070597, 2021). "Blocking the IL-9/Jak3 pathway has potential for treatment of both ALK+ ALCL and BIA-ALCL where tumor cells express IL-9 in an autocrine loop." (PMID 34503066, 2021). "Given the role of DNMTs in inhibiting tumor suppressors in ALK+ ALCL such as miRNA, they are also potential therapeutic co-targets with ALK in crizotinib resistant ALK(+) ALCL cells as previously shown." (PMID 33466277, 2021). "However, these drugs might be dissimilar in terms of the targeting profile, particularly against resistance mutations to previous TKIs and safety profiles, indicating that ALK-TKIs’ use may be influenced according to patients’ characteristics and the biological features of the tumor." (PMID 33352844, 2020). "Rearrangements of the anaplastic lymphoma kinase (ALK) gene are found in a subset of NSCLC patients and drive tumor growth." (PMID 32290439, 2020). "After 36 months of near complete response, the patient relapsed and a new tumor sample was obtained, finding the same STRN/ALK fusion." (PMID 32668761, 2020). "We have shown that recovered CTCs from selected patients with ROS1, ALK, and RET rearrangements carried genomic aberrations matching the primary tumor." (PMID 31947893, 2020). "Recently, a refractory ALK-positive ALCL patient has demonstrated prolonged responses to the PD-1 inhibitor, nivolumab, with dramatic reduction of physical pain and tumor size." (PMID 32059449, 2020). "Similarly, tumor-specific ALK fusions or mutants may also be recognized as neoantigens to our body." (PMID 32059449, 2020). "Crizotinib is believed to exhibit antitumor effects by inhibiting the kinases ALK, ROS1, and c-MET and suppressing the activation of these factors, tumor cell proliferation, and tumor angiogenesis." (PMID 32882995, 2020).
tumor (continued). "The tumor cell immunophenotype was positive for vimentin, EMA and negative for CK-pan, TTF-1, CAM5.2, S-100, calponin, SMA, desmin, ALK, CD31 and CD34." (PMID 32039736, 2020). "Here, we show that B7-H3 is upregulated in an ALK-induced T cell transformation model and ALCL cell lines, proving that B7-H3-directed CAR-T cells have potency when controlling ALCL tumor growth in vitro and in vivo." (PMID 33348781, 2020). "Another VHL-based ALK PROTAC TD-004 efficiently induced ALK degradation and inhibited the proliferation of SU-DHL-1 and H3122 cells in vitro, and reduced H3122 xenografted tumor growth in vivo." (PMID 32718354, 2020). "The first specimen of case #12 was tested twice with ALK FISH, but only 9–10% of tumor cells were identified as positive for ALK rearrangement, which is below the established cutoff value (≥15%) for a positive result." (PMID 32674491, 2020). "Although each tumor displayed a unique TIME, all tumors exhibited concomitant regression after treatment with an ALK-inhibitor." (PMID 33352665, 2020). "Since immunotherapy can be proposed alone or in combination with first-line chemotherapy in patients whose tumors are wild type for EGFR, ALK, ROS1, and BRAF, it is obligatory to obtain the PD-L1 status of tumor cells." (PMID 32294880, 2020). "Ninety percent of the tumours with these gene rearrangements were native KRAS, with a high proportion of MSI-H: 86.4%, 45.5% and 14.3% of the tumours with NTRK1, RET and ALK fusions, respectively." (PMID 32418154, 2020). "Currently, tumor genotyping is critical as personalized treatment for EGFR, ALK, ROS1, BRAF in the first-line setting." (PMID 32525942, 2020). "ALK-EML4 rearrangement is the consequence of a gene fusion in chromosome 2 between ALK gene and EML4 gene which leads to the activation of the tyrosine kinase domain of ALK protein that enhances tumor growth and proliferation." (PMID 32460789, 2020). "In ALK+ tumor cells, activation of the STAT3 driven by NPM-ALK fusion protein results in the increased expression of PD-L1." (PMID 33292562, 2020). "Lymph node involvement by ALK+ ALCL is characterized by cohesive clusters of large tumor cells within sinusoids and paracortical area, highlighted by CD30 and ALK immunostains." (PMID 33261174, 2020). "Three samples were previously analyzed by orthologous kit and determined to be ALK fusion‐positive (n = 2) by IHC and ROS1 fusion‐positive (n = 1) by RT‐PCR using FFPE tumor tissues." (PMID 32351019, 2020). "Non-invasive tumor molecular profiling is crucial to improve outcomes and quality of life of NSCLC patients whose tumors harbor a translocation involving ALK locus." (PMID 37362555, 2020). "Among 70 cases, only one ALK-fusion-positive lung ADC exhibited both moderate nuclear and cytoplasmic positive staining in 80% of tumor cells, which was considered as a false positive case." (PMID 31234388, 2019). "Forty-four unique fusions were identified in 40 (1.1%) of the 3,808 patients with circulating tumor DNA detected: RET (n = 6; 36% of all fusions detected), FGFR3 (n = 2; 27%), ALK (n = 10, 23%), NTRK1 (n = 3; 7%), ROS1 (n = 2; 5%), and FGFR2 (n = 1; 2%)." (PMID 33015522, 2019). "Through various prioritization strategies, we provide a core set of lincRNAs with a potential role in NB tumor biology, up- or downstream of the key NB driver genes MYCN, ALK and PHOX2B." (PMID 30952905, 2019). "All tumors were analyzed using an NGS multi-gene panel that expands the tumor genetic portrait, including genes such as BRAF, ERBB2, KRAS, and MET in addition to EGFR and ALK/ROS1, in accordance with recently updated recommendations." (PMID 30669267, 2019). "CCR4 was positive in the tumor cells of 9/15 ALK− ALCL cases (60%), 10/15 ALK+ ALCL cases (67%) and 6/10 cHL cases (60%)." (PMID 31581676, 2019). "Because it has a high homology with the kinase domain of ALK, ALK specific inhibitors, including crizotinib and ceritinib, revealed marked activity in ROS1-positive tumours." (PMID 31795465, 2019).